CBFB (core-binding factor subunit beta)
Diseases named in the same sentence as CBFB in open-access papers (continued):
Sharing a sentence is not in itself a finding about the gene and the disease.
bone metastasis (1 paper, 2022). Transfer of a neoplasm from its primary site to bones. "Notably, we observed elevated CBFB levels in the serum exosomes isolated from patients with bone metastasis compared with their nonmetastatic counterparts." (PMID 35903297, 2022).
bone tumours (1 paper, 2020). "Intracardiac injection of the CBFβ-CRISPR cells into mice resulted in a striking reduction of the number of mice developing bone tumours compared with controls." (PMID 32005976, 2020). "Initial experiments with the CBFβ-depleted cells resulted in bone tumours in which CBFβ-expression had recovered from the shRNA (data not shown)." (PMID 32005976, 2020).
cleft palate (1 paper, 2019). Cleft palate is a fissure type embryopathy that affects the soft and hard palate to varying degrees. "A human genome study demonstrated that CBFb haploinsufficiency owing to an interstitial deletion caused cleft palate and congenital heart anomalies in humans." (PMID 31171577, 2019). "A chromosomal fragile site of FRA16B, which colocalizes with breakpoints within CBFb at the chromosomal locus 16q22.1., is also involved in the inheritance of cleft palate." (PMID 31171577, 2019).
colon cancer (1 paper, 2023). "We expected that the transcription factors WRNIP1, ATF1, CBFB, and NR2F6, as well as the microRNAs miR-1-3p, miR-26b-5p, miR-164a-5p, and miR-9-5p, would play essential roles in metabolic abnormalities of cells in obese people and the development of colon cancer." (PMID 37711894, 2023).
experimental autoimmune encephalomyelitis (1 paper, 2026). An autoimmune demyelinating disease of the central nervous system that is produced experimentally in animals by the injection of homogenized brain or spinal cord in Freund's adjuvant. "This interaction is essential for RORγt function; mice with a RORγt mutant unable to bind CBFβ had impaired Th17 differentiation, were resistant to experimental autoimmune encephalomyelitis (EAE), and had defective thymocyte development." (PMID 41480759, 2026).
Infertility (1 paper, 2023). "From within the undifferentiated spermatogonia population, CBFβ regulates core frameworks that intersect different facets of germline maturation that when disrupted, lead to adult infertility." (PMID 38020932, 2023).
mastitis (1 paper, 2025). Inflammation of breast tissue during lactation or postpartum due to an obstructed duct or infection. "The bta-miR-145/CBFB pathway plays a role in Staphylococcus aureus-induced mastitis by influencing inflammatory responses and self-protective mechanisms." (PMID 39795030, 2025).
myeloma (1 paper, 2021). "Six TFs (CXXC1, BPTF, MAZ, KLF13, CBFB and RFX5) were identified as showing higher connectivity in all myeloma subgroups compared to ND PC, thus exemplifying the process of existing TF ‘re-wiring’ in MM." (PMID 34521827, 2021). "Similarly, myeloma cells appear to be addicted to CBFB and ZNF384 which have not been linked to myeloma PC biology thus far." (PMID 34521827, 2021).
neurofibroma (1 paper, 2019). An intraneural or extraneural neoplasm arising from nerve tissues and neural sheaths. "Last, pharmacological inhibition of RUNX/core-binding factor β (CBFB) activity significantly reduced neurofibroma volume in vivo." (PMID 31032403, 2019). "The efficacy of Ro5-3335 on mouse neurofibroma growth suggests that disruption of RUNX/CBFB interaction or targeting RUNX gene cluster might provide a novel therapeutic strategy for patients with neurofibroma." (PMID 31032403, 2019). "Targeting disruption of RUNX/CBFB interaction might provide a novel therapy for patients with neurofibroma." (PMID 31032403, 2019). "We also showed that pharmacological inhibition of RUNX/CBFB activity significantly reduced mouse neurofibroma growth in vivo, implicating a novel signaling pathway involving RUNX1/3 repression of Pmp22 in neurofibroma initiation and/or maintenance." (PMID 31032403, 2019). "It is different from the Runx1 genetically conditional knockout, in which RUNX1 has no function but CBFB function is undisturbed, and the compensated Runx3 gene produces RUNX3 that can bind to CBFB to achieve RUNX transcriptional activities and contribute to neurofibroma formation." (PMID 31032403, 2019).
cancer (38 papers, 2009 to 2026). A tumor composed of atypical neoplastic, often pleomorphic cells that invade other tissues. "To determine why CBFβ-depleted cells were less susceptible to TNF, we performed RNA-seq across two mouse cancer cell lines and compared our results to available published data in CBFβ-deficient human tumour cells." (PMID 39261596, 2024). "Mutations in other cancer genes including CBFB, IDH1, JAK1, KMT2A, SMAD4, and SMARCA4 were found in one MBC each." (PMID 29214215, 2017). "Across all cancer models, we found several Mt genes downregulated in CBFβ-deficient cells, including Mt1 and Mt2 (mouse) and MT1A, MT1E, MT1F, MT1G, MT1M, MT1X, and MT2A (human), further suggesting that metal ion homoeostasis is substantially altered in these cells." (PMID 39261596, 2024). "Indeed, the loss of CBFβ significantly reduced the capacity of metastatic cancer cells to invade osteoblast cultures in vitro and to form osteolytic lesions in vivo." (PMID 32005976, 2020). "Aberrant expression of CBFβ proteins has been linked to pathological events in cancer cells." (PMID 31610798, 2019). "We found that 7 out of 11 animals injected with the control cells developed tumours in the hind limbs, with numerous cancer-induced bone lesions detected, compared with three out of seven animals injected with CBFβ-CRISPR." (PMID 32005976, 2020). "Among these proteins, cyclin-dependent kinase 12 (CDK12) and core-binding factor subunit beta (CBFB) were overexpressed in tumors, which were consistent with their oncogenic role in certain types of cancer." (PMID 33287876, 2020). "Recently, CBFB and RUNX1 mutations have been identified as drivers in a variety of cancer types, including breast, ovarian, and prostate cancer." (PMID 31061501, 2019). "Among them, the CBFB oncogene has been documented into the COSMIC cancer Gene Census, a gene category for which mutations have been causally implicated in cancer." (PMID 26870154, 2015). "The transcription factor RNT-1 and its DNA binding partner BRO-1 (homologues of the mammalian cancer-associated stem cell regulators RUNX and CBFβ, respectively) are known rate-limiting regulators of seam cell proliferation." (PMID 21829390, 2011). "A comparison of IHC staining for CBFB and CD45 (a pan-leukocyte marker) indicated that CBFB was also expressed by a subset of stromal cells, in particular lymphocytes, including lymphocytes infiltrating both normal epithelia and cancer." (PMID 19156145, 2009). "Another example of this class is CBFB, discussed in detail in the next section, as a cancer driver." (PMID 37085483, 2023). "Noting how critical RUNX and CBFβ are in normal homeostasis and development, it is not surprising that these genes are frequently altered and mutated in a multitude of cancers." (PMID 36831308, 2023). "Notably, we observed that silencing CBFB in MDA-MB-436 cells resulted in the reduced expression of EMT regulator Snail, metastasis/cancer stem cell marker CD44, and bone metastasis–associated markers OPN and Runx2." (PMID 35903297, 2022). "Together our findings demonstrate that CBFβ can determine the plasticity of the metastatic cancer cell phenotype, suggesting that its regulation in different micro-environments may play a key role in the establishment of metastatic tumours." (PMID 32005976, 2020). "Together our findings demonstrate that the CBFβ complexes can determine the plasticity of the metastatic cancer cell phenotype, suggesting that their regulation in different micro-environments may play a key role in the establishment of metastatic tumours." (PMID 32005976, 2020).
cancer (continued). "Because transcription activity is difficult to target, the role of CBFB in translation regulation may be therapeutically exploited for cancer treatment." (PMID 31061501, 2019). "Expression of CBFβ is essential for cancer cell invasion and migration, indicating that CBFβ may have an oncogenic function in tumor etiology." (PMID 31610798, 2019). "For example, the deletion of the chromosome 16, the 19q13.2–19q13.43 regions, and the chromosome 21 are significantly correlated with underexpression of candidate cancer-suppressor genes, respectively CBFB or CDH11, TFPT and DSCR1, giving additional evidence in support of these events." (PMID 20711339, 2010). "In the case of FAM135B, FEV, CBFB, and CTNND2, the regulatory status inferred here is at odds with their documented cancer role, thereby indicating potential anomalous regulation whose resolution would be tractable to experimental investigation." (PMID 39484215, 2024). "Although much is known about the roles of CBFB and RUNX1 in the hematopoietic system and blood cancer, our knowledge of their functions and regulatory mechanisms in other tissues and cancers is very limited." (PMID 31061501, 2019). "PIK3CA, CBFB, CDC27, MAP3K1, and ESRRA were among the genes that were cancer drivers." (PMID 37454130, 2023). "In the context of metastasis in vivo this raises the possibility that interactions between cancer cells and the microenvironment influence the activity of RUNX/CBFβ, thereby shifting their phenotype toward the epithelial state and enabling the cells to colonise the new niche." (PMID 32005976, 2020). "Our transcript analyses of CBFB and SMARCC1 did not reveal any association, not even a trend, to recurrence of stage II cancer." (PMID 19156145, 2009). "For E2F3, SOX4, CBFB and SMARCC1, the transcript analyses were corroborated by an in-depth IHC analysis not only confirming their increased expression level, but also demonstrating their expression by the cancer cells." (PMID 19156145, 2009).
tumor (36 papers, 2009 to 2026). "Our study revealed that loss of core-binding factor subunit beta (CBFβ) enhances tumour cell resistance to T cell killing, mediated through T cell-derived TNF." (PMID 39261596, 2024). "All these CBFB mutants had undetectable protein levels while their mRNAs were comparable to that of CBFB wild type (WT), suggesting that these tumor-derived mutations destabilize CBFB and result in loss of function." (PMID 31061501, 2019). "Mutations in CBFB (3.3% across all tumours) were more frequent in IntClust3 (7.8%) and IntClust8 (9.7%), and less common in IntClust7 (1.0%), although patients within all these subtypes have relatively good outcomes." (PMID 27161491, 2016). "Given the strong enrichment of sgRNA targeting genes associated with cytokine signalling in our screen, we examined whether loss of CBFβ modulated tumour sensitivity to TNF; a key cytokine known to induce tumour cell death." (PMID 39261596, 2024). "Functional mutations in PIK3CA (odds ratio (OR)=0.58; 95% confidence interval (CI)=0.49–0.69), GATA3 (OR=0.77, CI=0.6–0.99), MAP3K1 (OR=0.52, CI=0.4–0.68), KMT2C (OR=0.69, CI=0.52–0.94) and CBFB (OR=0.56, CI=0.38–0.83) were associated with lower grade in ER+ tumours." (PMID 27161491, 2016). "The synthetic lethal interaction between VHL and CBFB provides a new route to target ccRCCs, and is supported by our murine xenograft models in which tumour growth is markedly inhibited." (PMID 39282259, 2024). "To validate that loss of CBFβ confers tumour cell resistance to CAR-T cell killing, we depleted CBFβ in MC38-HER2 tumour cells by electroporating cells with a CRISPR/Cas9-sgCbfb ribonucleoprotein (RNP) complex." (PMID 39261596, 2024). "To explore the mechanism by which deletion of CBFβ modulates tumour cell sensitivity to TNF, we compared the transcriptional profile of sgNT and sgCbfb cells by bulk RNA-sequencing (RNA-seq)." (PMID 39261596, 2024). "We further identified the transcription factor, CBFβ, as a positive regulator of tumour sensitivity to TNF-mediated cell death." (PMID 39261596, 2024). "Analyses of the surviving tumour cell population by flow cytometry confirmed significant enrichment of the CBFβ-depleted tumour cells under both conditions, further indicating that CBFβ regulates tumour cell sensitivity to T cell-derived TNF." (PMID 39261596, 2024). "Three RUNX transcription factors, RUNX1, RUNX2, and RUNX3, along with their cofactor CBFβ, exert tumor-related functions in a context-dependent manner." (PMID 37190031, 2023). "Knockdown of CBFB in the metastatic MDA-MB-436 cell line also resulted in reduced tumor growth and improved overall survival in a xenograft model." (PMID 36831308, 2023). "Using the ratio of non-synonymous to synonymous mutations (dN/dS value) for missense and truncating mutations, we found that many of the driver genes, including CBFB and ATG14, are potential tumor suppressor genes with high truncating mutations." (PMID 36831585, 2023). "Of therapeutic relevance, targeting CBFB resulted in decreased tumor burden and bone metastasis, downregulation of bone metastasis markers, and impaired regulation of oxidative stress–related proteins NAE1 and NOS1." (PMID 35903297, 2022).
tumor (continued). "The size of tumors formed in mice injected with CBFB-knockdown cells was significantly smaller at the indicated time points, compared with that of the control group, with a 3.16-fold difference in tumor size by week 4 (p < 0.01)." (PMID 35903297, 2022). "In this study, CBFB knockdown decreased tumor burden, bone metastasis, and markers of bone metastasis, including CXCR4, Snail, CD44, OPN, Runx2, and IL-6." (PMID 35903297, 2022). "Experiments using tumor samples derived from the tumor xenograft mouse models demonstrated that the expression of CBFB, OPN, Runx2, and CXCR4 proteins was significantly suppressed in CBFB-knockdown mice, compared with the control mice." (PMID 35903297, 2022). "RUNX family transcription factor 3 (AML2) forms a heterodimeric complex core-binding factor (CBF) with CBFB and functions as a tumor suppressor." (PMID 34828279, 2021). "Previously, we have shown that the repression of NOTCH3 is one of the mechanisms of the tumor suppressive functions of CBFB and RUNX1." (PMID 33945523, 2021). "Numbers of tumours in both control and CBFβ-depleted cells were similar, however tumour volume in the CBFβ-depleted cells was significantly less than the shNS cells." (PMID 32005976, 2020). "In summary, NOTCH3 repression contributes to the tumor suppressive function of the nuclear CBFB/RUNX1 complex." (PMID 31061501, 2019). "Overall, the IHC analysis indicated that the CBFB protein level was increased in tumours compared with normal mucosa." (PMID 19156145, 2009). "Cbfβ was also among the most significantly enriched overlapping genes, suggesting that loss of CBFβ promotes tumour cell resistance to T cell killing through a mechanism common to both CAR- and TCR-mediated tumour cell recognition." (PMID 39261596, 2024). "We identified that alteration of metal ion homoeostasis is a common feature of tumour cells lacking CBFβ although the underlying molecular basis remains to be defined." (PMID 39261596, 2024). "We have specifically concentrated in this review on our knowledge of RUNX/CBFβ within the context of the breast epithelia, but it is exciting that these proteins may also have an important role (direct or indirect) within the tumor microenvironment." (PMID 36831308, 2023). "We used an MDA-MB-436-innoculated tumor xenograft mouse model for silencing CBFB." (PMID 35903297, 2022). "In addition, mice bearing CBFB-knockdown tumor cells had a significantly higher survival rate (week 4: control, 10% vs. CBFB-knockdown, 60%)." (PMID 35903297, 2022). "In this study, we identified TAp73 as another mechanism for the tumor suppressive function of CBFB." (PMID 33945523, 2021). "Effect of TAp73 overexpression on the tumor formation of CBFB_KO and RUNX1_KO MCF10A cells." (PMID 33945523, 2021). "Ro5-3335, a RUNX1/CBFβ inhibitor, induced tumor cell death and led to tumor volume shrinkage." (PMID 34359780, 2021). "The goal of this study is to further investigate the tumor suppressive function of CBFB." (PMID 33945523, 2021).